ABCG4 (ATP binding cassette subfamily G member 4)
Description:
ATP-dependent transporter of the ATP-binding cassette (ABC) family that may be involved in the cellular efflux of sterols, in particular cholesterol and desmosterol (a cholesterol precursor), to high-density lipoprotein (HDL). May play an important role in the removal of amyloid-beta peptides from brain, in a process that can be antagonized by desmosterol. However it is unclear whether ABCG4 can directly transport amyloid-beta peptides or whether peptide export may be facilitated due to changes in the membrane lipid environment (By similarity). Induces apoptosis in various cells.
Synonyms: WHITE2
Tractability: Antibody: UniProt places it where antibodies can reach, with high confidence; its Gene Ontology location is reachable by antibodies, with high confidence; UniProt predicts a signal peptide or a membrane-spanning region. PROTAC: ubiquitination databases record sites on it.
Gene: Protein-coding gene on chromosome 11 (119,149,052 to 119,162,653, forward strand). Ensembl gene ENSG00000172350.
Subcellular location: Cell membrane; Cytoplasmic vesicle membrane; Endosome membrane
Pathways (Reactome):
Transport of small molecules: ABC transporters in lipid homeostasis
Gene Ontology:
Molecular function: ATP hydrolysis activity; identical protein binding; protein binding; protein heterodimerization activity; protein homodimerization activity; ABC-type sterol transporter activity; ABC-type transporter activity; ATP binding; protein dimerization activity
Biological process: cholesterol efflux; cholesterol homeostasis; cellular response to high density lipoprotein particle stimulus; positive regulation of cholesterol biosynthetic process; positive regulation of cholesterol efflux; regulation of DNA-templated transcription; sterol transport; transmembrane transport
Cellular component: plasma membrane; cytoplasmic vesicle; cytoplasmic vesicle membrane; endosome membrane; endosome; membrane
Genetic constraint (gnomAD): Loss-of-function variants: 35 observed, 66.86 expected, observed/expected ratio (o/e) 0.52, 90% interval 0.4 to 0.69. The upper end of that interval is the gene's LOEUF score, 0.69, which puts it in group 2 of 6, group 1 being the genes least tolerant of losing a copy. Missense variants: 610 observed, 885.22 expected, observed/expected ratio (o/e) 0.69, 90% interval 0.64 to 0.74. Synonymous variants: 326 observed, 364.31 expected, observed/expected ratio (o/e) 0.89, 90% interval 0.82 to 0.98.
Homologues: Orthologues: chimpanzee ABCG4 (100% identical), macaque ABCG4 (100% identical), pig ABCG4 (99% identical), rabbit ABCG4 (99% identical), dog ABCG4 (98% identical), mouse Abcg4 (97% identical), guinea pig ABCG4 (96% identical), rat Abcg4 (95% identical), tropical clawed frog abcg4 (83% identical), zebrafish abcg4a (80% identical), zebrafish abcg4b (78% identical), Drosophila melanogaster Atet (53% identical), and 10 more. Paralogues in human: ABCG1 (72% identical), ABCG2 (28% identical), ABCG5 (27% identical), ABCG8 (23% identical).
Diseases named in the same sentence as ABCG4 in open-access papers:
ABCG4 is named in the same sentence as 26 diseases in open-access papers, as found by Europe PMC text mining. Sharing a sentence is not in itself a finding about the gene and the disease. The quoted sentences say what the papers report.
Alzheimer disease (5 papers, 2016 to 2024). A progressive, neurodegenerative disease characterized by loss of function and death of nerve cells in several areas of the brain leading to loss of cognitive function such as memory and language. "Similar results were found for ABCG4, a transporter that has been indicated in regulating sterol levels in the brain and has been implicated in Alzheimer’s disease as an exporter of amyloid-β peptides from cells." (PMID 31159502, 2019). "However, ABCG4 is expressed almost exclusively in brain and has been linked to Alzheimer’s disease (AD)." (PMID 31159502, 2019). "ABCG1 is expressed in both neurons and astrocytes, whereas ABCG4 has been detected in neurons and astrocytes, as well as microglia from patients with Alzheimer’s disease." (PMID 27196068, 2016). "ABCG1 and ABCG4 may inhibit the development of Alzheimer’s disease and can be targets for the treatment of Alzheimer’s disease." (PMID 27196068, 2016). "ABCG1 and ABCG4 may play important roles in suppression of Aβ generation and pathogenesis of Alzheimer’s disease." (PMID 27196068, 2016). "However, reports proposed a role for ABCG4 in Alzheimer’s disease (AD), demonstrating increased expression of ABCG4 in microglial-like cells in the brain of AD patients." (PMID 27228027, 2016). "ABCG1 and ABCG4 could be new targets for prevention and treatment of Alzheimer’s disease." (PMID 27196068, 2016). "In this study, we examined the effects of ABCG1 and ABCG4 on amyloid precursor protein (APP) processing, the product of which, amyloid β (Aβ), is involved in the pathogenesis of Alzheimer’s disease." (PMID 27196068, 2016). "In conclusion, our data show that loss of Abcg4 did not lead to acceleration of the pathology in a mouse model of Alzheimer’s disease, and that the kinetics of Aß clearance from the brain were not affected by the presence or absence of Abcg4." (PMID 37333297, 2023).
atherosclerosis (3 papers, 2016 to 2019). A disease characterized by the build-up of fatty material and calcium deposition in the arterial wall resulting in partial or complete occlusion of the arterial lumen. "With the decrease in cholesterol efflux caused by Abcg4 deficiency, Abcg4-/- mice exhibit MkP proliferation and expansion, thrombocytosis, increased platelet/leukocyte aggregation and accelerated atherosclerosis." (PMID 31234305, 2019). "A more recent study suggested a protective role for ABCG4 in the defense against thrombosis and atherosclerosis." (PMID 27228027, 2016).
prostate carcinoma (2 papers, 2021 to 2026). A carcinoma that arises from epithelial cells of the prostate gland. "Simvastatin induces glutathione (GSH)-mediated suppression of ABCG4 (which causes efflux of intracellular doxorubicin and cisplatin) levels, increasing the sensitivity of prostate cancer cells to cisplatin and leading to the suppression of tumor growth." (PMID 34065757, 2021).
cognitive (1 paper, 2024). "Besides, ABCG4 is related to genes of cognitive dysfunction, adhesion spot, neuroinflammation, and energy metabolism in the brain cortex." (PMID 38514755, 2024).
malaria (1 paper, 2019). Malaria is a serious and sometimes fatal disease caused by a parasite that commonly infects a certain type of mosquito which feeds on humans. "In particular, the ABCG4 gene, a member of the G subfamily, has consistently been shown to be up-regulated in response to insecticide treatments in the mosquito malaria vector Anopheles stephensi (both adults and larvae)." (PMID 31462239, 2019).
neuroblastoma (1 paper, 2023). Neuroblastoma (NB) is the most common solid, extracranial childhood tumor. "In the INFORM dataset, only two other transporters (ABCA3 and ABCG4) were significantly (P < 0.05) and relevantly (FC > 2) upregulated in relapsed neuroblastoma compared to other entities." (PMID 36181342, 2023).
non-small cell lung carcinoma (1 paper, 2015). A group of at least three distinct histological types of lung cancer, including non-small cell squamous cell carcinoma, adenocarcinoma, and large cell carcinoma. "However, the association between the expression of the ABC sub-family G member 4 (ABCG4) and prognosis in patients with non-small-cell lung cancer (NSCLC) remains unclear." (PMID 26270652, 2015).
psoriasis (1 paper, 2025). An autoimmune condition characterized by red, well-delineated plaques with silvery scales that are usually on the extensor surfaces and scalp. "There is currently no direct evidence to support a direct association between ABCG4 and the progression of psoriasis." (PMID 40560938, 2025).
T cell lymphoma (1 paper, 2024). "ABCC4 and ABCG4 were significantly up-regulated in human NK/T cell lymphoma YTS and SNK-6 cells compared with normal NK cells." (PMID 38178117, 2024). "Based on gene expression regulation technology, overexpression of ABCC4 and ABCG4 can induce epirubicin (EPI) and cisplatin (DDP) resistance in human NK/ T cell lymphoma YTS cells and reduce cell apoptosis." (PMID 38178117, 2024).
type 2 diabetes (1 paper, 2017). "In type 2 diabetes human pancreatic islets, as compared with non-diabetic controls, up - regulation of insulin and expression of miRNA-463-3p and down-regulation of ABCG4 were observed and their expression levels were closely related." (PMID 28761062, 2017).
tumor (3 papers, 2015 to 2025). "ABCG4 positivity rate was higher in NSCLC than in normal lung tissues (48.6% vs. 0%, P<0.001) and ABCG4 expression was significantly associated with poor differentiation, higher tumor node metastasis (TNM) stage, and adenocarcinoma histological type (all P<0.001)." (PMID 26270652, 2015).
brain disease (2 papers, 2013 to 2025). "Disruption of brain cholesterol homeostasis occurs in other neurological, neurodegenerative and neurodevelopmental disorders and suggests a potential role of ABCG4 in brain disorders." (PMID 24278214, 2013).
cancer (1 paper, 2024). A tumor composed of atypical neoplastic, often pleomorphic cells that invade other tissues. "The mechanism of drug resistance by ABCG4 probably involves alterations in the pH value around cancer cells." (PMID 38731966, 2024).
infection (1 paper, 2017). The state of being infected such as from the introduction of a foreign agent such as serum, vaccine, antigenic substance or organism. "Furthermore, in infection with type II parasites, up-regulation of Abcg4, a Chl export protein, and of liver X receptor alpha (Nr1h3), was revealed." (PMID 28459857, 2017).
neurological disorders (1 paper, 2016). "However, the uncovered phenomenon, the ABCG4-induced apoptosis, brings up a novel area to be explored, which may assist in better understanding of dysfunctional clearance mechanisms in certain neurological disorders." (PMID 27228027, 2016).
ABCG4 also shares sentences with these, for which no sentence is quoted: Glucose intolerance (2 papers); Insulin resistance (2); adenocarcinoma (1); brain tumors (1); connective tissue disorder (1); Hypercholesterolemia (1); lung adenocarcinoma (1); lung squamous cell carcinoma (1); neurodevelopmental disorder (1); Obesity (1); Thrombocytosis (1).